HHIP (hedgehog interacting protein)
Diseases named in the same sentence as HHIP in open-access papers (continued):
Sharing a sentence is not in itself a finding about the gene and the disease.
glioma (1 paper, 2019). A benign or malignant brain and spinal cord tumor that arises from glial cells (astrocytes, oligodendrocytes, ependymal cells). "Similarly, TMZ sensitivity caused by SUV39H2 deficiency was also partially reversed by the knockdown of HHIP in glioma cells." (PMID 31636512, 2019). "In summary, these data demonstrate that SUV39H2 regulates tumor growth and TMZ sensitivity in an HHIP-dependent manner in glioma cells." (PMID 31636512, 2019). "The low expression of HHIP is epigenetically regulated, as its promoter is overly methylated in glioma." (PMID 31636512, 2019). "In our study, we found that SUV39H2 regulated the activity of the GLI1 reporter, and there was a reverse correlation between SUV39H2 and HHIP expression in glioma." (PMID 31636512, 2019). "SUV39H2 knockdown represses cell growth and promotes cell chemosensitivity in glioma cells by upregulating HHIP expression." (PMID 31636512, 2019). "The low expression or inactivation of HHIP has been reported in many tumors, including glioma." (PMID 31636512, 2019). "Moreover, the reverse correlation between SUV39H2 and HHIP in glioma cells was further confirmed by analyzing the GSE4290 database." (PMID 31636512, 2019). "Furthermore, to determine whether SUV39H2 regulates glioma progression in an HHIP-dependent way, we transfected shSUV39H2 or the combination of shSUV39H2 and shHHIP into U251 cells." (PMID 31636512, 2019). "However, the regulatory mechanism of HHIP in glioma is still unclear." (PMID 31636512, 2019). "To further confirm that HHIP was regulated by SUV39H2 in glioma, we examined the expression of SUV39H2 and HHIP in xenograft tumors using immunohistochemistry (IHC) staining." (PMID 31636512, 2019). "In the GSE4290 database, we also found that SUV39H1 has a reverse correlation with HHIP, which indicates that SUV39H2 and SUV39H1 may have mutual compensatory effects on tumor growth and chemosensitivity in glioma." (PMID 31636512, 2019).
head and neck carcinoma (1 paper, 2017). A carcinoma that arises from the head and neck region. "Thus, our observation that HHIP undergoes methylation may partly explain the mechanism of this loss in head and neck cancers." (PMID 27553089, 2017). "Further investigations should determine the detailed diagnostic significance of methylation of ZIC4, HHIP, and DACT2 in head and neck carcinomas." (PMID 27553089, 2017). "Further investigations should determine the diagnostic significance of methylation of ZIC4, HHIP, and DACT2 in head and neck carcinomas." (PMID 27553089, 2017). "Few studies investigated the epigenetic regulation of Shh signaling in head and neck carcinomas; thus, we aimed to assess whether known negative regulators of this pathway (HHIP, PTCH1, SUFU, ZIC1, ZIC4) undergo methylation in HNSCC." (PMID 27553089, 2017). "The analysis of the occurrence of gene promoter methylation in head and neck carcinoma cell lines indicated that CXXC4, DACT2, HHIP, ZIC1, and ZIC4 are methylated in these tumors." (PMID 27553089, 2017).
head and neck squamous cell carcinoma (1 paper, 2017). A squamous cell carcinoma that arises from any of the following anatomic sites: lip and oral cavity, nasal cavity, paranasal sinuses, pharynx, larynx, and salivary glands. "In summary, we report that CXXC4, DACT2, HHIP, ZIC1, and ZIC4 are methylated in head and neck squamous cell carcinomas." (PMID 27553089, 2017).
Hyperinsulinemia (1 paper, 2023). An increased concentration of insulin in the blood. "According to the results of EHC, hyperinsulinemia resulted in a significant decrease in serum adipoq levels, while circulating HHIP levels did not change in normal controls." (PMID 36769536, 2023).
Insulin resistance (1 paper, 2023). Increased resistance towards insulin, that is, diminished effectiveness of insulin in reducing blood glucose levels. "Serum HHIP levels were higher in insulin resistance (IR) and PCOS women." (PMID 36769536, 2023).
limb ischemia (1 paper, 2025). A ischemia that involves the limb. "In mice, deleting CARMN caused impariment in capillary growth and blood flow recovery after limb ischemia, an effect that was reversed by restoring miR-143-3p or silencing the Hedgehog inhibitor HHIP." (PMID 41090354, 2025).
lymphocytic leukemia (1 paper, 2014). "A report demonstrating participation of this pathway in regulating myeloid leukemia supports further research into the role of HHIP in lymphocytic leukemia." (PMID 24959420, 2014).
medulloblastoma (1 paper, 2018). A malignant, invasive embryonal neoplasm arising from the cerebellum. "Furthermore, analysis of patient samples revealed an enrichment of several hedgehog pathway genes, such as GLI2, GLI3 and HHIP in cells from medulloblastoma patients expressing high SCARB1 levels." (PMID 29352211, 2018).
melanoma (1 paper, 2019). A malignant, usually aggressive tumor composed of atypical, neoplastic melanocytes. "THOC2 expression was positively correlated with PDE4D, PIK3CA, GNAI1, and HHIP expression in melanoma tissues." (PMID 31680623, 2019). "In addition, correlation analysis showed that THOC2 expression was correlated with PDE4D, PIK3CA, GNAI1, and HHIP expression in melanoma tissues." (PMID 31680623, 2019). "Our results showed that THOC2 inhibition significantly reduced the expression of PDE4D, PIK3CA, GNAI1, ADCY1, HHIP and ADORA2A in melanoma cells." (PMID 31680623, 2019).
osteoporosis (1 paper, 2023). A condition of reduced bone mass, with decreased cortical thickness and a decrease in the number and size of the trabeculae of cancellous bone (but normal chemical composition), resulting in increased fracture incidence. "The elderly with osteoporosis exhibited lower methylation levels of the HHIP promoter area than the control group, and this corresponded with reduced HHIP expression and increased P1NP and β-CrossLaps, suggesting that HHIP is linked to osteoporosis in the elderly." (PMID 37056287, 2023).
pancreatitis (1 paper, 2019). Inflammation of the pancreas. "Hedgehog interacting protein (Hhip) is essential for islet formation and beta-cell proliferation during pancreatic development; abnormally elevated Hhip expression has been linked to human pancreatitis." (PMID 31371780, 2019).
pneumonia (1 paper, 2021). An acute, acute and chronic, or chronic inflammation focally or diffusely affecting the lung parenchyma, caused by an infection in one or both of the lungs (by bacteria, viruses, fungi, or mycoplasma.). "Among genes upregulated in ACE2-expressing AT2 cells, we identified genes that are highly pertinent to lung epithelial biology and disease such as HHIP (lung branching and COPD), FGG (fibrosis, pneumonia, and inflammation), and C4BPA (complement system, pneumonia, and infection)." (PMID 33809063, 2021).
polycystic ovary syndrome (1 paper, 2023). A disorder that manifests as multiple cysts on the ovaries. "With the improvement of metabolic disorder and hyperandrogenemia, the level of circulating adipoq was found to increase significantly in all three treatment groups, but a significant decrease in serum HHIP levels was observed only in the TZDs and GLP-1RA groups." (PMID 36769536, 2023). "However, the relationship between HHIP and polycystic ovary syndrome (PCOS) or abnormal sex hormones remains unknown." (PMID 36769536, 2023).
respiratory failure (1 paper, 2017). The significant impairment of gas exchange within the lungs resulting in hypoxia, hypercarbia, or both, to the extent that organ tissue perfusion is severely compromised. "Knockout of HHIP in mice led to the inhibition of lung bud branching and neonatal respiratory failure." (PMID 28929109, 2017).
serous ovarian cancers (1 paper, 2020). "This analysis revealed an enrichment of SHH pathway genes, including GLI1, GLI2, HHIP, PTCH1, and PTCH2, in SSTs as compared to high-grade serous ovarian cancers and other sex cord-stromal tumors." (PMID 31896750, 2020).
small cell lung carcinoma (1 paper, 2013). Small cell lung cancer (SCLC) is a highly aggressive malignant neoplasm, accounting for 10-15% of lung cancer cases, characterized byrapid growth, and early metastasis. "Amongst these, the ones recently discovered to contribute in small cell lung cancer development are Smoothened (SMO), Rab23, platelet-derived growth factor alpha (PDGFRα), hedgehog interacting protein (HIP) and hepatocyte nuclear factor 3-beta (HNF3β)." (PMID 23692865, 2013).
thyroid cancer (1 paper, 2018). "We next performed a wound-healing/migration assay to investigate the effect of the HHIP G516R mutation on thyroid cancer cell behavior." (PMID 30241415, 2018). "Next, we determined to investigate the functional effect of the HHIP G516R mutation on thyroid cancer cell properties to understand the biological role of this mutation in human thyroid cancer." (PMID 30241415, 2018). "All these data indicate that the HHIP G516R mutation promotes tumor aggressiveness in thyroid cancer compared to HHIP-WT." (PMID 30241415, 2018). "In this study, we identified the novel HHIP G516R mutation by performing WES of locally advanced thyroid cancer tissues, including primary tumors and metastatic lymph nodes." (PMID 30241415, 2018). "Despite this, the mutation was detected in human locally advanced thyroid cancers, which might suggest the long-term effect of mutant HHIP G516R." (PMID 30241415, 2018). "HHIP G516R, a missense mutation, could be a representative example for the intra-tumor heterogeneity of locally advanced thyroid cancer, which can be a potential future therapeutic target for this disease." (PMID 30241415, 2018). "Interestingly, 12 or 24 h after the monolayers were scratched, the sizes of the wounds were significantly smaller in 8505C cells transfected with HHIP-G516R than in cells transfected with the control vector or HHIP-WT, indicating that the HHIP G516R mutation promotes thyroid cancer cell migration." (PMID 30241415, 2018). "In fact, in vitro experiments showed that HHIP G516R promoted thyroid cancer cell proliferation and migration." (PMID 30241415, 2018). "In vitro, HHIP G516R increased cell proliferation and promoted cell migration in thyroid cancer cells." (PMID 30241415, 2018). "In addition, this study first identified HHIP G516R (G1546A), which promotes tumor aggressiveness in thyroid cancer cells." (PMID 30241415, 2018). "The other interesting finding was that the FLAG signal was much higher in HHIP G516R transfected lysates compared to HHIP-WT transfected lysates, indicating interaction of the G516R mutant protein with SHH might increase the HHIP protein amount in thyroid cancer cells." (PMID 30241415, 2018).
ulcerative colitis (1 paper, 2020). An inflammatory bowel disease involving the mucosal surface of the large intestine and rectum. "In humans, a GLI1 nonsynonymous polymorphism is strongly associated with ulcerative colitis, where areas of colonic inflammation display reduced expression of the HH target genes GLI1, PTCH, and HHIP." (PMID 32196081, 2020).
tumor (32 papers, 2012 to 2025). "Overall, our findings clarified ncRNAs-mediated down-regulation of HHIP which was associated with poor prognosis and tumor immune infiltration in CRC." (PMID 37568084, 2023). "In this study, the expression, the survival prognosis or mechanism of HHIP in CRC and the association between HHIP and tumor immune infiltration in CRC were studied." (PMID 37568084, 2023). "The results showed that HHIP promoter was significantly hypermethylated in tumor as compared to normal tissue, and the methylation was significantly associated with HHIP gene expression." (PMID 27015549, 2016). "However, from the genes' biological functions, the identified HHIP gene was closely related to cancer stem cells, which were key drivers of tumor progression, so the inference that HHIP caused the subtype divergence became reasonable." (PMID 38666214, 2024). "CircFAM114A2 exerts a tumor suppressor role in HCC through miR‐630/HHIP axis, and may be served as a potential diagnostic and therapeutic biomarker for HCC patients." (PMID 37039160, 2023). "Given cancer stem cells' tumor-initiating capacity, it was understandable that HHIP drove the LUAD subtype development here." (PMID 38666214, 2024). "On the one hand, some studies have indicated that HHIP is down-regulated in various tumors and influences the tumor’s biological functions." (PMID 37568084, 2023). "To further confirm the function of HHIP in tumor immune, we ascertained the expression correlation of HHIP with biomarkers of immune cells in CRC on the basis of TCGA data." (PMID 37568084, 2023). "The TIMER database was used to explore the expression level of HHIP in human cancers, which showed that HHIP was downregulated in a variety of tumor tissues." (PMID 36482325, 2022). "GEPIA analysis showed a significant lower expression of RUNX1T1 and HHIP in the tumor samples (n = 163) compared to the normal tissues (n = 207)." (PMID 34157951, 2021). "GLI1 upregulates VEGFR2, as the main effector of HH-promoting angiogenesis, and HHIP in mature vessels, while HHIP is downregulated in ECs engaged in angiogenesis and tumor neovessels." (PMID 34940041, 2021). "TCF21 and HHIP expression levels were also significantly lower in tumour tissues than in the non‐tumour tissues of the mice." (PMID 32525231, 2020). "Studies have shown that while HHIP mRNA is expressed in normal tissues, its expression is decreased in some tumour tissues." (PMID 32525231, 2020). "Our analysis showed that HHIP was mainly located in the nucleoplasm of A‐431, U‐2 OS and U‐251 MG cells, and TCF21 and HHIP were significantly downregulated in human tumour tissues when compared to the levels in the corresponding adjacent tissues." (PMID 32525231, 2020). "HHIP, a new tumor suppressor, is involved in the occurrence and development of many tumors, but its specific mechanism of its role in each malignant tumor needs further study." (PMID 31765425, 2019). "Studies have shown that HHIP mRNA is expressed in normal tissues, but its expression decreased in some tumor tissues." (PMID 31765425, 2019). "Hedgehog interacting protein (HHIP) negatively regulates the Hh pathway by binding to the hedgehog protein and acts as a tumor suppressor." (PMID 31636512, 2019). "In general, decreased HHIP expression has been indicated in several tumors, suggesting a potential role of HHIP in tumor suppression." (PMID 30241415, 2018). "Of note, when comparing UHRF1 expression levels with previously published expression levels of the tumor suppressor gene HHIP in primary tumor tissues and the three cell lines, we also found a significant inverse correlation of both genes (inset)." (PMID 29507645, 2018).
tumor (continued). "HHIP expression has been found silenced by promoter hypermethylation in several types of tumor, including gastrointestinal, hepatocellular carcinoma, medulloblastoma, and pancreatic neoplasm." (PMID 27015549, 2016). "Comparing the relative gene expressions between tumor and normal parts (the T/N ratio), only HHIP was significantly reduced, while other HH pathway components largely unchanged (T/N closed to 1)." (PMID 27015549, 2016). "We found that cells overexpressing HHIP exhibited defective tumor initiation and growth activity in nude mice." (PMID 27015549, 2016). "Like previous results, HHIP gene expression was reduced in these tumor cells as compared to normal fibroblast (NF) obtained from normal tissue of patients." (PMID 27015549, 2016). "We observed other markedly under-expressed genes (P<0.05) included tumour-suppressor candidates that negatively regulate the Hh pathway (SUFU, GAS1, RAB23) and genes encoding inhibitory proteins (HHIP, HHAT)." (PMID 22361633, 2012). "Similarly, the impact on tumor cell viability over 72 h was found more pronounced upon targeting HHIP with G4 alone (P < 0.0001), although still significantly lessened in the MIX 4 genes condition (P < 0.0001) relative to NO G control." (PMID 37120619, 2023). "Furthermore, the relationship between HHIP and tumor immune infiltration in CRC remains undetermined." (PMID 37568084, 2023). "Mechanistically, circFAM114A2 overexpression could enhanced the tumor suppressor HHIP via “miR‐630 sponge”." (PMID 37039160, 2023). "In addition, HHIP expression level was significantly correlated with tumor immune cell infiltration, biomarkers of immune cells, and immune checkpoint expression." (PMID 37568084, 2023). "Examination of main Hh target genes individually shows higher levels of GLI2, PTCH1, SMO, BOC, and HHIP transcripts in the tumor-adjacent tissue as compared to the bulk tumor, further supporting the importance of the tumor-adjacent tissue in the activity of Hh signaling." (PMID 31658643, 2019). "Moreover, our current findings elucidated that HHIP might carry out its carcinostasis role by increasing tumor immune cell infiltration and immune checkpoint expression." (PMID 37568084, 2023). "Based on these results, we found that HHIP might play tumor suppressive roles in human cancer." (PMID 37568084, 2023). "Low HHIP expression level in tumor tissues could predict poor prognosis in HCC patients." (PMID 36482325, 2022). "We then found that HHIP promoter was epigenetically silenced in LAC, like previous reports in other cancer types, The analysis of 492 LAC patient samples showed that HHIP promoter was significantly hypermethylated in tumor, and the methylation level was significantly associated with gene expression." (PMID 27015549, 2016). "PD-L1(PDCD1), CTLA4 and PD1 (CD274) are important immune checkpoints which are in charge of tumor immune escape.Taken the potential carcinogenic function of HHIP in CRC into consideration, the correlation of HHIP with PD-L1, CTLA4 and PD1 was assessed." (PMID 37568084, 2023). "Human hedgehog interacting protein (HHIP), a negative regulator of Hh signalling frequently underexpressed in several tumours, showed an extremely high level of expression in NBCCS-HFs suggesting a compensatory mechanism acting on Hh pathway." (PMID 34831015, 2021). "Meanwhile, a Chi-square test determined that low HHIP expression was significantly correlated with gender, cancer subtype, TNM stage and tumor size." (PMID 31765425, 2019). "Chi-square test results showed that the low expression of HHIP was correlated with gender, cancer type, TNM stage and tumor size." (PMID 31765425, 2019).